ULK1 (unc-51 like autophagy activating kinase 1)
Diseases named in the same sentence as ULK1 in open-access papers (continued):
Sharing a sentence is not in itself a finding about the gene and the disease.
nutritional deficiency (4 papers, 2016 to 2022). "Cellular stress states such as oxidative stress injury, hypoxia, and severe nutritional deficiency, were reported to suppress the activity of mTOR complex and activate the Unc-51 like kinase 1/2 (ULK1/2) signaling." (PMID 36072293, 2022). "However, once IS occurs, cerebral cells suffer from nutritional deficiency, ULK1 undergoes autophosphorylation, and mTORC1 dissociates from the ULK1 complex to relieve its suppression." (PMID 35807426, 2022). "Under conditions of nutritional deficiency, AMP-activated protein kinase (AMPK) phosphorylates the Ser 317 and Ser 777 sites of ULK1 to activate autophagy." (PMID 35418866, 2022).
osteoarthritis (4 papers, 2013 to 2024). A noninflammatory degenerative joint disease occurring chiefly in older persons, characterized by degeneration of the articular cartilage, hypertrophy of bone at the margins and changes in the synovial membrane. "The upregulation of autophagy genes, especially Ulk1, might be associated with increased cell turnover in cartilage and protection from osteoarthritis." (PMID 24002865, 2013).
schizophrenia (4 papers, 2018 to 2026). A major psychotic disorder characterized by abnormalities in the perception or expression of reality. "Exosome sequence analysis and genotyping suggested that rare ULK1 variants were involved in susceptibility to schizophrenia." (PMID 41510670, 2026).
Stroke (4 papers, 2021 to 2025). Sudden impairment of blood flow to a part of the brain due to occlusion or rupture of an artery to the brain. "Similarly, immunoblotting showed a marked increase in p-AMPKα, p-ULK1 (Ser 317), and active caspase-3 plus a greater reduction in p62/SQSTM1, p-mTOR, mTOR, p-S6, p-4E-BP, and p-ULK1 (Ser757) in the ipsilateral cerebral cortex of CrT–/y mice 24 hours after stroke." (PMID 34324436, 2021).
thyroid cancer (4 papers, 2021 to 2024). "This study shows that AdipoRon can induce autophagy in thyroid cancer cells via AdipoR2 and upregulating ULK1, thereby inhibiting tumor growth." (PMID 39349421, 2024). "Our study observed differences in ULK1 phosphorylation and autophagy marker protein changes in thyroid cancer cells." (PMID 39349421, 2024). "Thyroid cancer cell lines with silenced ULK-1 or that had been pretreated with an autophagy inhibitor were treated with AdipoRon." (PMID 39349421, 2024). "AdipoRon induced autophagy in thyroid cancer cells via AdipoR2 and by upregulating ULK1." (PMID 39349421, 2024). "This suggests that AdipoRon activates ULK1 via AdipoR2 to induce autophagy in thyroid cancer cells." (PMID 39349421, 2024). "In vitro, we silenced ULK1 in thyroid cancer cell lines, and used clone formation and scratch assays to demonstrate that AdipoRon regulates tumor cell proliferation and migration capabilities in a ULK1-dependent manner." (PMID 39349421, 2024). "Five hundred and sixty-seven miRNAs associated with nine autophagy proteins (ULK1, ATG16L1, MAP1LC3B, PRKAA1, ATG12, ATG 14, ATG5, mTOR and BECN1) were identified, of which sixty-two are accompanied by thyroid cancer, and only miR-125b is associated with the autophagy modulation in this pathology." (PMID 36980957, 2023). "Findings showed that AdipoRon no longer affected mitochondrial membrane potential in thyroid cancer cells with silenced ULK-1 or that had been pretreated with an autophagy inhibitor." (PMID 39349421, 2024).
Arthritis (3 papers, 2019 to 2025). Inflammation of a joint. "The autophagy-associated protein, microtubule-associated protein light chain 3b (LC3b) has been reported to be upregulated, and while UNC51-like kinase 1 (ULK-1) is downregulated in experimental arthritis mice." (PMID 35003139, 2021). "Furthermore, its water and ethyl acetate extracts also result in the normalization of abnormal ULK-1 protein levels, thereby alleviating arthritis symptoms." (PMID 35003139, 2021). "Taken together results demonstrate a non-canonical ULK-1 independent autophagy pathway being followed after arthritis induction that is probably responsible for apoptosis resistance." (PMID 31728208, 2019). "In our study, the administration of CFA dramatically lowered the articular gene expression of ULK-1, Beclin-1, and ATG-7 as compared to control rats, leading to significant downregulation in the autophagy process, supporting the hypothesis of autophagy involvement in hindering arthritis severity." (PMID 40350466, 2025).
asthma (3 papers, 2023 to 2025). "Wuhu Decoction promotes autophagy in lung tissue DCs through AMPK/ULK1 signaling pathway to alleviate RSV-induced asthma inflammation." (PMID 37090692, 2023). "Additionally, the ULK1/Atg9a/Rab9 signaling pathway has been identified as a key regulator of mitochondrial oxidative stress and inflammation in asthma, with ULK1 activation promoting inflammasome activation and Golgi apparatus fragmentation, further intensifying pulmonary inflammation." (PMID 40598285, 2025).
chronic myeloid leukemia (3 papers, 2020 to 2025). "TRAF6 catalyzed K63-linked polyubiquitination of ULK1 can stabilize ULK1 to promote activation of autophagy, which is related to drug resistance in chronic myeloid leukemia patients." (PMID 33004065, 2020).
diabetic cardiomyopathy (3 papers, 2022 to 2023). Diabetic cardiomyopathy is a disorder of the heart muscle in people with diabetes. "In the current study, excessive autophagy causes increased protein levels of ULK1, Beclin1, LC3II, Cathepsin D, and Fyco1 in diabetic cardiomyopathy, indicating the important role of these proteins in different stages of the autophagy process." (PMID 37764807, 2023). "Empagliflozin may attenuate diabetic cardiomyopathy-related myocardial injury by promoting the catabolism of BCAA and inhibiting mTOR/p-ULK1 to enhance autophagy." (PMID 37149696, 2023). "In conclusion, our study indicated that empagliflozin could protect diabetic cardiomyopathy by up-regulating PP2Cm, promoting catabolism of BCAA, and downregulating mTOR/p-ULK1, thereby up-regulating ULK1 and increasing autophagy." (PMID 37149696, 2023).
Insulin resistance (3 papers, 2017 to 2021). Increased resistance towards insulin, that is, diminished effectiveness of insulin in reducing blood glucose levels. "This could indicate insulin resistance and implies that another mechanism than mTORC1/ULK1 is responsible for suppressing autophagy." (PMID 28252104, 2017).
laryngeal carcinoma (3 papers, 2024 to 2025). Carcinoma that arises from the laryngeal epithelium. "This is suggestive of possible regulation by NSD1 of not only ULK1 at the transcriptional level but also of its downstream target Beclin-1 in laryngeal cancer cell types." (PMID 38346948, 2024).
lipid metabolism disorders (3 papers, 2025). "KSJG granules can improve lipid metabolism disorders caused by NAFLD through the same mechanism as that of OP by activating the AMPK/ULK1 (Ser555) pathway to upregulate autophagy levels." (PMID 40894198, 2025). "Cel promotes macrophage autophagy by activating the AMPK/ULK1 pathway, ameliorates lipid metabolism disorders, and suppresses the inflammatory response, thereby stabilizing atherosclerotic plaques." (PMID 41347171, 2025).
lupus (3 papers, 2013 to 2025). "Reduced phosphorylation of ULK1 might suggest activated autophagosome causing better clearance of damaged cells in rapamycin-treated lupus mice." (PMID 39234308, 2024). "lpr_Control (1.42 ± 0.66 a.u.)had higher phosphorylation of ULK1 when compared with MpJ_Control (0.72 ± 0.28 a.u.)which may suggest a reduced influx of autophagy in lupus mice." (PMID 39234308, 2024).
lymphoma (3 papers, 2016 to 2020). A malignant (clonal) proliferation of B- lymphocytes or T- lymphocytes which involves the lymph nodes, bone marrow and/or extranodal sites. "We found that this combined therapy triggered enhanced autophagy, notably through the relieved inhibition of the ULK1 protein, and ultimately led to lymphoma cell death." (PMID 33066037, 2020). "The expression of key autophagy-relevant proteins (e.g. Beclin-1, ULK1) and LC3 processing was increased in cHL cells, even in lymphoma cases." (PMID 27366944, 2016).
myocardial infarction (3 papers, 2022 to 2025). Gross necrosis of the myocardium, as a result of interruption of the blood supply to the area, as in coronary thrombosis. "Analysis of human blood sample sequencing datasets and mouse myocardial infarction sequencing datasets as well as cardiomyocyte hypoxia experiments indicated that FRGs ALOX5, CAMKK2, KDM6B, LAMP2, PTEN, PTGS2, and ULK1 may be potential biomarkers of AMI." (PMID 36407421, 2022).
steatosis (3 papers, 2019 to 2023). Increased lipid within the cytoplasm of cells. "Reduced expression of ULK1 was confirmed by immunofluorescence and immunoblot assay in liver tissue from patients with steatosis and NASH compared with normal livers." (PMID 37739179, 2023). "Irbesartan initiated the autophagy flux and relieved steatosis by modulating the PKC/AMPK/ULK1 axis, thus both autophagy and lipophagy are dynamic processes in hepatocytes." (PMID 31191364, 2019). "Intriguingly, hepatic mRNA levels of JMJD3, TFEB, ULK1, ATG7, and ATGL, were all decreased in both simple steatosis and advanced NASH-fibrosis patients compared to normal subjects." (PMID 32042044, 2020).
acute kidney injury (2 papers, 2021 to 2024). Sudden and sustained deterioration of the kidney function characterized by decreased glomerular filtration rate, increased serum creatinine or oliguria. "Recent studies have demonstrated that the activation of uncoupling protein 1 (UCP1) can mitigate lipid accumulation, thereby attenuating the progression of acute kidney injury via the AMPK/ULK1/autophagy pathway." (PMID 39544947, 2024).
acute leukemia (2 papers, 2022 to 2024). A clonal (malignant) hematopoietic disorder with an acute onset, affecting the bone marrow and the peripheral blood. "Pomegranate, the main phenolic compound in pomegranate peel, andrographis paniculata can induce autophagy production in acute leukemia by up-regulating ULK1 expression." (PMID 38887520, 2024). "ULK1 can also interact with plant extracts to play a role in acute leukemia." (PMID 38887520, 2024).
allergic rhinitis (2 papers, 2025). Inflammation of the nasal mucous membranes caused by an IgE-mediated response to external allergens. "Ginsenoside Rh1 is involved in the inflammatory process of allergic rhinitis through the AMPK/ULK1/FUNDC1 signaling axis." (PMID 40535916, 2025). "In allergic rhinitis models, Rh1’s therapeutic efficacy operates through activation of the AMPK/ULK1/FUNDC1 pathway, which mediates mitochondrial autophagy and subsequently reduces NLRP3 inflammasome activation while restoring Th1/Th2 balance." (PMID 41155644, 2025).
anemia (2 papers, 2018 to 2019). A reduction in the number of red blood cells, the amount of hemoglobin, and/or the volume of packed red blood cells. "Knock out of the autophagic regulators, ULK1, Atg4, Atg7, or FIP200, or mitophagy-specific receptor, NIX, inhibited erythropoiesis leading to anemia in mice while inducing myeloid expansion." (PMID 30546074, 2019). "A mild anemia was also found in cases where ULK1 is absent that led to a delay in the removal of mitochondria and ribosomes in erythroid cells." (PMID 29967662, 2018).
autoimmune disease (2 papers, 2013 to 2025). A disorder resulting from loss of function or tissue destruction of an organ or multiple organs, arising from humoral or cellular immune responses of the individual to their own tissue constituents. "Therefore, the interactions and balance between the AMPK, mTOR and ULK1 proteins are pivotal in regulating autoimmune diseases." (PMID 40599805, 2025).
Barrett esophagus (2 papers, 2022 to 2025). Esophageal lesion lined with columnar metaplastic epithelium which is flat or villiform. "The reversal of EMT phenotypes by RAPA and DAPT further confirms that the effects of SNHG1 are mediated via the ULK1-Notch1 axis, highlighting its potential as a therapeutic target in Barrett’s esophagus." (PMID 40629071, 2025).
breast tumors (2 papers, 2024 to 2026). "Unc-51 like kinase 1 (ULK1) deficiency has been found to enhance invasive potentials and osteolytic bone metastasis of breast tumors via attenuating mitophagy." (PMID 39035027, 2024).
colitis (2 papers, 2022). Inflammation of the colon. "Ginsenoside Rd ameliorated colitis by inducing p62-driven mitophagy-mediated NLRP3 inflammasome inactivation and upregulating of AMPK/ULK1 signaling pathway in DSS-induced murine colitis model." (PMID 35454101, 2022).
Coma (2 papers, 2020 to 2022). The complete absence of wakefulness and consciousness, which is evident through a lack of response to any form of external stimuli. "In contrast, total AMPK and p-ULK1 S317 significantly increased after the coma." (PMID 33173467, 2020). "When D-BHB was administered after the coma, SQSTM1/p62 degradation was enhanced and ULK1 S317 phosphorylation was reduced, increasing cell survival." (PMID 33173467, 2020). "No changes in p-mTOR S2448 and p-ULK1 S757 were found neither in the cortex nor the hippocampus of D-BHB-treated animals as compared to the Coma group." (PMID 33173467, 2020).
cyst (2 papers, 2012 to 2025). A sac-like closed membranous structure that may be empty or contain fluid or amorphous material. "Additionally, mTORC1 inhibits autophagy via Unc-51-like kinase 1 (ULK1) suppression, a critical initiator of the autophagy cascade, further contributing to cyst growth and metabolic dysregulation." (PMID 40801635, 2025).
dementia (2 papers, 2023 to 2025). Loss of intellectual abilities interfering with an individual's social and occupational functions. "Conversely, CSF ULK1 levels were higher in FTLD-MCI compared to AD-dementia." (PMID 39972393, 2025). "Conversely, levels of CSF ULK1, the main autophagy initiator, were increased in FTLD-MCI compared to AD dementia patients, and serum ULK1 levels were increased in FTLD dementia relative to AD-MCI and CU individuals." (PMID 39972393, 2025). "Our findings indicated a significantly lower CSF PINK1 and ULK1 levels in FTLD compared to AD, with FTLD dementia showing particularly low CSF PINK1 levels compared to AD-dementia." (PMID 39972393, 2025). "In our study, we found increased CSF ULK1 levels in FTLD-MCI compared to AD dementia and AD-MCI, and increased serum ULK1 in FTLD dementia compared to CU and AD-MCI." (PMID 39972393, 2025). "By reducing mTOR activity and directly activating ULK1, AMPK also leads to the formation of autophagosomes and the degradation of Tau and APP, thus achieving the purpose of treating dementia." (PMID 37189611, 2023).
depression (2 papers, 2022 to 2025). "Abnormal expression of ULK1 has been observed in depression, suggesting its potential role in the pathogenesis of the disorder." (PMID 41311024, 2025). "ULK1 was downregulated in frontal cortex (FC) and hippocampus (Hp) of male depression model rats exposed to chronic mild stress." (PMID 41311024, 2025). "Furthermore, ULK1 has been identified as a potential therapeutic target for depression, with its modulation showing promise in preclinical models." (PMID 41311024, 2025). "In this study, the present findings reveals that the expressions of ULK1, MAPK14, WIPI1, and DUSP1 were associated with the immune system, thereby participated in the pathogenesis of depression and could provide potential targets for future treatments." (PMID 41311024, 2025). "ULK1 was a promising therapeutic target within the autophagy framework, ULK1/Beclin‐1 initiation complex act as targeted autophagy modulation as a revolutionary pathway for developing more effective and personalised interventions for depressive disorders." (PMID 41311024, 2025). "Analyzing the protein regulatory network of FEZ1, in a series of interaction proteins obtained, it is found that the three autophagy-related proteins SCOC, ULK1, and NBR1 might play a role in depression." (PMID 35435132, 2022).
dyslipidemia (2 papers, 2019 to 2025). "Finally, eleven CpG sites were associated with metabolic syndrome: cg08862778 (MTOR), cg11322849 (INS), cg07199894 (ULK1), cg11658986-cg04149773 (ADCY6), cg14862787-11301281 (CREB5), cg14844401-cg20300093 (ADCY5), cg01284192 (IGF1R) and cg08128650 (RELA)." (PMID 30926763, 2019). "We propose that in ApoE−/− mice—characterized by severe dyslipidemia and oxidative stress—macrophage AMPK/ULK1 signaling may exist in a primed or sensitized state, rendering it particularly responsive to Cel." (PMID 41347171, 2025).
esophageal neoplasm (2 papers, 2015 to 2022). "Our study shows that the tumor suppressor effect of SJC is related to promoting autophagy in esophageal tumor cells via the AMPK/ULK1 signaling pathway." (PMID 36120378, 2022).
gestational diabetes mellitus (2 papers, 2022 to 2024). "An increased expression of ULK1 has been observed in the placental tissue of women with gestational diabetes mellitus (GDM) when compared to healthy women." (PMID 38396708, 2024).
head and neck squamous cell carcinoma (2 papers, 2022). A squamous cell carcinoma that arises from any of the following anatomic sites: lip and oral cavity, nasal cavity, paranasal sinuses, pharynx, larynx, and salivary glands. "Recent studies have demonstrated ULK1 O-GlcNAcylation via immunoprecipitation in neonatal mouse cardiomyocytes, in a model of starvation-induced liver autophagy and upon lentiviral transduction of a head and neck squamous cell carcinoma (HNSCC) with HPV genes." (PMID 36359905, 2022).
inflammatory bowel disease (2 papers, 2020 to 2022). A spectrum of small and large bowel inflammatory diseases of unknown etiology. "Unravelling differences between ULK1 and ULK2 could lead to a better understanding of how ULK-type specific dysregulation affects autophagy and other cellular processes that have been implicated in diseases such as inflammatory bowel disease and cancer." (PMID 32616830, 2020).
liver diseases (2 papers, 2022 to 2025). "A large body of evidence has indicated that the abnormal expression of ULK1 is involved in multiple human organ diseases, including neurological diseases, infections, cardiovascular diseases, cancer, and liver diseases." (PMID 36743936, 2022). "This could involve ULK1 kinase inhibition, activation of counteracting phosphatases, or disruption of the p62-KEAP1 interaction, all of which may have therapeutic potential as approaches for liver diseases." (PMID 40437287, 2025).
lung diseases (2 papers, 2024 to 2025). "Recent studies denote that ULK1 signaling may be implicated in the development of several pulmonary disorders." (PMID 39544928, 2024). "Extensive studies have revealed the role of ULK1 and its potential to treat lung diseases." (PMID 40033510, 2025). "Investigating the function of ULK1 signaling in lung diseases may facilitate the creation of targeted therapies designed to regulate autophagy and improve outcomes for patients with these conditions." (PMID 39544928, 2024).
mastitis (2 papers, 2021 to 2023). Inflammation of breast tissue during lactation or postpartum due to an obstructed duct or infection. "Our other experiments showed that GPR109A could regulate the phosphorylation of ULK1, Beclin and AMPK to improve mastitis and enhance the blood milk barrier." (PMID 34803497, 2021).
metastatic melanoma (2 papers, 2022 to 2024). A melanoma that has spread from its primary site to another anatomic site. "Consistent with its role in T cell cytotoxicity resistance observed in our CRISPRa screening, ULK1’s expression was correlated with a poor survival rate in patients with metastatic melanoma." (PMID 36475797, 2022).
non-alcoholic fatty liver disease (2 papers, 2020 to 2024). "Remarkably, in non-alcoholic fatty liver disease patients, hepatic expression of JMJD3, ATG7, LC3, and ULK1 is substantially decreased." (PMID 32042044, 2020).